PLAT (plasminogen activator, tissue type)
Diseases named in the same sentence as PLAT in open-access papers (continued):
Sharing a sentence is not in itself a finding about the gene and the disease.
tumor (113 papers, 1989 to 2025). "High PLAT expression was significantly associated with a poor tumor prognosis, and PLAT was also coexpressed with ITGB3 and TNC." (PMID 39754146, 2025). "Conversely, tumor-associated macrophages (TAM) expressed high levels of PLAU and PLAUR, and tumor-associated endothelial cells expressed high levels of PLAT, F2R and SERPINE1." (PMID 35053621, 2022). "High PLAT expression was associated with poor tumor prognosis." (PMID 39754146, 2025). "Given the profound and detrimental prognostic impact of F3, PLAT, and C1S, coupled with their elevated expression in tumor tissues, targeting these genes or their associated pathways may represent a promising therapeutic strategy." (PMID 39179711, 2024). "Furthermore, the expression levels of F3, PLAT and C1S in tumor cells are linked to sensitivity to specific drugs." (PMID 39179711, 2024). "While urokinase-type plasminogen activator, tissue-type plasminogen activator, and their receptors are commonly activated during tumour progression, fibrinolysis inhibitors are also upregulated." (PMID 40332145, 2025). "Targeting the FABP1-PLG-PLAT axis inhibits fatty acid metabolic reprogramming and tumor angiogenesis by inhibiting fatty acid binding protein 1 (FABP1) and its downstream plasminogen (PLG) - tissue plasminogen activator (PLAT) signaling pathway." (PMID 41281744, 2025). "In summary, PLAT was upregulated in tumor tissues in the TCGA database, and the omics sequencing data for PC9GR-PC9 was downregulated after mono- or combined therapeutic administrations." (PMID 39754146, 2025). "PLAT expression had a tendency of increased expression in the primary tumour and mesenteric when compared to the normal SI in each category of fibrosis but lacked significance." (PMID 40998421, 2025). "PLAT is upregulated in tumor tissues in the TCGA database analysis, and the histological sequencing data analysis of PC9GR-PC9 confirmed that it is downregulated after mono- or combination drug administration." (PMID 39754146, 2025). "Accessing the breast cancer patient tumour data from TCGA revealed that methylation of these two CpG sites is highly negatively correlated with PLAT expression." (PMID 37753740, 2024). "PECAM1 expression was also closely associated with ETS1/PLAT and CD274 (PDL1)/IFNGR1, indicating close involvement of tumor angiogenesis with unique proteolysis and tumor immunity." (PMID 38557819, 2024). "For example, the PLAT gene is expressed primarily in three clusters of primary tumor samples, including Epithelial-3, Epithelial-6, and Epithelial-9." (PMID 36598637, 2023). "We examined the mRNA levels of six genes that constitute the «core» tumor coagulome: F3, PLAU, PLAT, PLAUR, F2R and SERPINE1 encoding TF, uPA, tPA, uPAR, PAR-1 and PAI-1, respectively, in tumors from TCGA." (PMID 35053621, 2022). "Among the remaining nine genes, FABP and PLAT were decreased in tumor tissues, while the others exhibited the opposite distribution." (PMID 34805164, 2021). "Although it is common that urokinase-type plasminogen activator, tissue-type plasminogen activator as well as their receptor were activated during tumor growth, activation of the fibrinolysis inhibitors is also observed." (PMID 34433454, 2021). "PLAT has a role in promoting fibrinolysis and antagonizing thrombosis and is likely involved in tumor oncogenesis and progression." (PMID 34621293, 2021). "Circ_0084097 and its host gene PLAT are negatively correlated with metastasis of tumours significantly related to the stomach (p < 0.05)." (PMID 31552107, 2019). "Correlation analysis of circ_0084097/PLAT expression in tumour tissue samples of GIST patients and their clinical factors." (PMID 31552107, 2019). "PLAT revealed higher expression in three tumor cases, six healthy tissues, and two cases had a similar PLAT expression level." (PMID 31717665, 2019).
tumor (continued). "The integration from our omics-based research provides a four molecular pathway foundation (ANXA2/HMGA1/POU3F1; NFRSF13/GSN; TMOD3/RAI14/VWF; and PLAT/PLAU) behind HO-1 regulation of tumor cytoskeletal cell compartments." (PMID 28032857, 2016). "Interestingly, however, this analysis identified PLAT expression as an outlier with higher intra-tumor than inter-tumor heterogeneity." (PMID 40003901, 2025). "PLAT is significantly upregulated in tumor tissues in the TCGA database (P < 0.05)." (PMID 39754146, 2025). "High expression of PLAT is significantly related to a poor tumor prognosis." (PMID 39754146, 2025). "PLAT, a secreted serine protease, has been demonstrated to enhance cancer cell migration and invasion, whilst CCL3, a gene coding for a ligand for CC motif chemokine receptor 1 and 5 (CCR1 and CCR5), has been implicated in promoting tumour growth." (PMID 40998421, 2025). "This suggests that F3, PLAT, and C1S may enhance immune responses within the tumor microenvironment." (PMID 39179711, 2024). "F7 and PLAT showed slightly lower mRNA expression levels in tumor tissues." (PMID 38955935, 2024). "Additionally, gene–drug association analysis identified ciclosporin, ouabain and 6- mercaptopurine, which all exhibit immunosuppressive properties, as potential therapeutic options for tumor patients exhibiting high F3, PLAT or C1S expression, respectively." (PMID 39179711, 2024). "Our findings reveal that F3, PLAT, and C1S exhibit positive correlations with tumor stemness in certain cancer types, suggesting that these VRGs may exert detrimental effects in those specific cancer types." (PMID 39179711, 2024). "While 5 genes were downregulated in tumor tissues, including PLAT, ERBB2, CEACAM1, NOX4, and UCHL1." (PMID 37056778, 2023). "PLAT was also negatively correlated with the tumour diameter (p < 0.05), indicating that circ_0084097 and PLAT may be related to the early stage of stomach stromal tumour." (PMID 31552107, 2019). "Both COL1A1 and PLAT have been found to increase the proliferation of tumour cells." (PMID 19200380, 2009). "Finally, we demonstrated that PROX1 and other vascular factors, such as VEGFC (vascular endothelial growth factor C), BAIAP2 (BAI1 associated protein 2), FGF2 (fibroblast growth factor 2), and PLAT (plasminogen activator) are differently expressed in FTC human tissues compared to non-tumor tissues." (PMID 31717665, 2019). "We, therefore, confirmed the ALDH1A3‐dependent regulation of PLAT, PLAU, and SERPINB2 by RT‐qPCR and visualized the co‐expression correlation of the genes with ALDH1A3 in the patient tumour data." (PMID 37753740, 2024). "Specifically, in TNBC cells we find that ALDH1A3 can transcriptionally regulate PLAT, PLAU, and SERPINB2; however, considering both the cell line and patient tumour data, the strongest overall evidence was between ALDH1A3 and PLAT/tPA." (PMID 37753740, 2024). "To examine the relationship between tPA and tumour progression in vivo, we generated stable knockdown of PLAT/tPA in MDA‐MB‐231 cells and these cells has reduced tPA activity and had reduced plasmin and invasion activity." (PMID 37753740, 2024). "Similarly, hypoxia-induced LBH, a highly conserved transcription cofactor, participates in embryonic development and promotes tumor progression of GBM, and hypoxia upregulates the expression of PLAT in GBM cells." (PMID 35874629, 2022). "Strikingly, when integrating the transcriptome under HO-1 modulation with the HO-1 interactome, a framework of four main molecular pathways arose as the foundation for the regulation of the tumor cell protrusive forces: ANXA2/HMGA1/POU3F1; NFRSF13/GSN; TMOD3/RAI14/VWF; PLAT/PLAU." (PMID 28032857, 2016).
tumor (continued). "Other studies have confirmed that the PLAT may be significantly correlated with the immune status of patients with BRCA by regulating the expression of many immune molecules and influencing immune infiltration in the tumor microenvironment." (PMID 40809023, 2025). "Our study discovered that F3, PLAT and C1S exhibit the highest expression in subtype C6, known as “TGF-beta dominant,” which is characterized by elevated TGF-beta signaling that may suppress immune response and promote tumor growth." (PMID 39179711, 2024).
cancer (100 papers, 1997 to 2025). A tumor composed of atypical neoplastic, often pleomorphic cells that invade other tissues. "PLAT encodes tissue-type plasminogen activator and contributes to cancer cell migration and tissue remodeling." (PMID 39179711, 2024). "Our analysis highlighted F3, PLAT and C1S as genes associated with poorer prognosis across various cancers." (PMID 39179711, 2024). "PLAT encodes a tissue type plasminogen activator, and it has been shown that its activation target, plasmin, can inhibit brain metastasis by releasing FasL from astrocytes to promote cancer cell death, as well as inactivating the adhesion molecule L1CAM important for cancer spreading." (PMID 34948172, 2021). "We noted the dominant contribution of cancer cells to the expression of the “core coagulome”, i.e., the CRGs directly upstream of thrombin/plasmin activation (F3, PLAT and SERPINE1)." (PMID 40003901, 2025). "Using multiplex immunofluorescence staining, we confirmed elevated expression of F3, PLAT and C1S in many cancer tissues as compared to paired para-cancerous tissues." (PMID 39179711, 2024). "In the majority of cancer types, F3, PLAT, and C1S exhibited significantly stronger positive correlations with stromal, immune and ESTIMATE scores compared to F2, PLG, and SERPINC1." (PMID 39179711, 2024). "Our data show that PLAT itself has a low toxicity effect on RBCs because its main target in cancer cells is DNA." (PMID 36829507, 2023). "Spearman correlation of the 16 hypoxia genes and 151 chemo drugs in the Genomics of Drug Sensitivity in Cancer database revealed that the expression of DCBLD2, PLEC, S100A11, PLAT, PPAP2B and LAMC2 was associated with resistance to most chemotherapies." (PMID 35155430, 2022). "Vorinostat (HDAC2 inhibitor) and aminocaproic acid (PLAT inhibitor) both inhibited a SARS-CoV2 ‘prey protein’ and targeted a gene within the pathways in cancer and extracellular matrix (ECM)/ECM-associated proteins PES pathways, respectively." (PMID 33720009, 2021). "The PLAT gene has been studied in the context of cancer in several papers." (PMID 39869563, 2025). "Notably, relatively lower methylation levels for SERPINC1 and PLAT were observed in most cancers than that in normal groups." (PMID 39179711, 2024). "This suggests that the role of F3, PLAT and C1S in cancer immunology may be more complex than initially assumed." (PMID 39179711, 2024). "In summary, our findings provide a bioinformatics perspective on VRGs in pan-cancer, highlighting the pivotal roles of F3, PLAT and C1S, which could potentially be therapeutically exploited and targeted in several cancers, especially in GBMLGG." (PMID 39179711, 2024). "Furthermore, our multiplex immunofluorescence staining confirmed the increased protein levels of C1S, F3, and PLAT in cancer tissues compared to their paired para-cancerous tissues." (PMID 39179711, 2024). "The analysis of the cancer coagulome found expression of genes encoding six pro‐coagulant and fibrinolytic factors (F3, PLAU, PLAT, PLAUR, SERPINB2, and SERPINE1) in The Cancer Genome Atlas, and correlated with VTE incidence in 32 cancer types in a previously reported Dutch study." (PMID 37147936, 2023). "Besides, CDKN2C and ID2 are downregulated while IL6, BIRC3, PLAT, PPARG, and CEBPB are upregulated in three candidate TCM associated with Transcriptional misregulation in the cancer pathway." (PMID 34490085, 2021). "PLAT, Plasminogen Activator Tissue Type, a serine protease, induces the conversion of inert zymogen plasminogen to protease plasmin, which degrades the surrounding matrix, allowing cancer cells to migrate to distant sites." (PMID 30098229, 2018). "Interestingly, degradation of BM including type IV COL is rate-limiting step for cancer intravasation into blood in metastasis, and PLAT as well as PLAU may be the initial members of the protease cascade." (PMID 38557819, 2024).
cancer (continued). "Our analysis identified that C1S, F3, and PLAT as genes with notably high expression, while PLG, SERPINC1, and F2 exhibited lower expression levels across most cancers." (PMID 39179711, 2024). "In OSCC, on average, cancer cells expressed high mRNA levels of F3, PLAU and PLAT, but little if any of PLAUR, F2R or SERPINE1." (PMID 35053621, 2022). "Several genes were found to be up-regulated including Nos2, PLAT, and CD34 many of which are involved in Wnt/β catenin signaling, a pathway known to drive cell proliferation and regulate cell-cell adhesion in cancer 29–32." (PMID 31796785, 2019). "Here, we showed that ADAM9 also contributes the functions of angiogenesis and vascular remodeling for cancer progression through regulation of VEGFA, ANGPT2, and PLAT via in vitro and in vivo experiments." (PMID 29118335, 2017). "Further, AIWrap identified six new genes (VCX3A, CALHM5, ZMYND10, FOXE1, PLAT, FADD) which could be related to smoking in cancer patients, thus providing an opportunity for identifying previously unknown biological functions." (PMID 37853338, 2023).
cardiovascular disease (32 papers, 2006 to 2025). "We found that ANGPT2, PLAT (tPA), SERPINE1 (PAI-1), and VEGFA, which are involved in cardiovascular disease, were influenced in ADAM9 knockdown cells." (PMID 29118335, 2017).
infection (32 papers, 2008 to 2025). The state of being infected such as from the introduction of a foreign agent such as serum, vaccine, antigenic substance or organism. "In a previous study, coagulation-related genes, specifically in the fibrinolysis pathway, were modulated by B. besnoitia in vitro infection, with the upregulation of several molecules with fibrinolytic properties such as plasminogen activator, tissue type (PLAT) at 12 h post-infection (hpi)." (PMID 34294155, 2021).
PLAT also shares sentences with these, for which no sentence is quoted: intracranial hemorrhage (88 papers); ischemia (67); Cerebral ischemia (66); intracerebral hemorrhage (60); hemorrhage (55); Hypertension (46); cerebral infarction (38); Sepsis (35); pulmonary embolism (28); Hyperglycemia (26); depression (25); atrial fibrillation (24); infarction (23); acute myocardial infarction (22); angioedema (18); metabolic syndrome (18); thrombotic disease (18); Alzheimer disease (17); hemorrhagic stroke (17); brain injury (16); hematoma (16); empyema (14); brain edema (13); Cognitive impairment (13); epilepsy (11); multiple sclerosis (10); pneumonia (10); Thromboembolism (10); hyperlipidemia (9); injury (9).
A further 298 diseases each share a sentence with PLAT in 9 papers or fewer.